LINC00160 (long independently transcribed non-coding RNA 160)
Synonyms: C21orf52; NCRNA00160
Gene: Long non-coding RNA gene on chromosome 21 (34,723,807 to 34,737,204, reverse strand). Ensembl gene ENSG00000230978.
Diseases named in the same sentence as LINC00160 in open-access papers:
LINC00160 is named in the same sentence as 7 diseases in open-access papers, as found by Europe PMC text mining. Sharing a sentence is not in itself a finding about the gene and the disease. The quoted sentences say what the papers report.
breast carcinoma (6 papers, 2019 to 2023). "LINC00160 has been reported to be transcriptional targets of ERα and exhibit prognostic significance in breast cancer survival." (PMID 32921632, 2020). "LINC00160 was served as a putative biomarker for ER-positive breast cancers by epigenetic analysis and indicated prognostic significance in connection with the survival of breast cancer patients." (PMID 36077657, 2022). "LINC00160 was shown to be direct transcriptional targets of estrogen receptor-α in breast cancer." (PMID 32315986, 2020). "Additionally, downregulation of LINC00160 resulted in suppression of cancer cells proliferation, which indicated that LINC00160 could act as a biomarker for endocrine response in breast cancer therapy." (PMID 32921632, 2020). "Luminal A types showed overexpression of LINC00160, and abundance of DSCAM‐AS1 was reported in luminal B subtypes of breast cancer." (PMID 30959550, 2019).
renal cell carcinoma (2 papers, 2020). "In this study, we identified that LINC00160 was associated with sunitinib resistance in renal cell carcinoma." (PMID 32921632, 2020). "LINC00160 mediates sunitinib resistance in renal cell carcinoma via SAA1 that is implicated in STAT3 activation and compound transportation, which offers an opportunity for targeted intervention and molecular therapies in the future." (PMID 32921632, 2020).
kidney cancer (1 paper, 2020). Primary or metastatic malignant neoplasm involving the kidney. "We have illustrated that LINC00160 was upregulated in kidney cancer samples." (PMID 32315986, 2020).
renal carcinoma (1 paper, 2020). A carcinoma arising from the epithelium of the renal parenchyma or the renal pelvis. "Collectively, these results indicated that LINC00160 silencing could inhibit renal cancer growth." (PMID 32315986, 2020).
tumor (2 papers, 2020). "This study is the first study to demonstrate the functional role of LINC00160 in ccRCC tumor progression." (PMID 32315986, 2020). "We uncovered that LINC00160 knockdown in 786-O cells significantly decreased tumor weight and tumor volume." (PMID 32315986, 2020). "In our study, the separation of nuclear and cytoplasmic RNA assays revealed that LINC00160 was predominantly localized in nucleus in two cell lines, which indicates that LINC00160 probably perform transcriptional regulation role to exert its influence on tumor progression." (PMID 32315986, 2020). "LINC00160‐depleted MCF‐7/Tax and BT474/Dox cells showed decreased tumour growth rates in nude mice." (PMID 32652877, 2020).
LINC00160 also shares sentences with these, for which no sentence is quoted: cancer (1 paper); clear cell renal cell carcinoma (1).